TNF (tumor necrosis factor)
Diseases named in the same sentence as TNF in open-access papers (continued):
Sharing a sentence is not in itself a finding about the gene and the disease.
Barrett esophagus (16 papers, 2009 to 2025). Esophageal lesion lined with columnar metaplastic epithelium which is flat or villiform. "Increased expression of TNF-α and its receptor have been demonstrated in the progression of Barrett’s metaplasia to adenocarcinoma." (PMID 32408627, 2020). "The protein expression of TNF-α is also notably elevated in Barrett's oesophagus tissue samples and even more so in AC tissue." (PMID 20550712, 2010). "Individuals with Barrett's oesophagus also exhibit signs of chronic inflammation indicated by higher circulating levels of inflammatory mediators such as IL-6 and TNF-α." (PMID 20550712, 2010). "Notably, elevated TNF-α and NF-κB expressions have been reported in both BE and esophageal adenocarcinoma (EAC), suggesting their involvement in the progression from BE to malignancy." (PMID 40149421, 2025). "However, studies on esophageal adenocarcinoma cells suggest that TNF-alpha activates GLI proteins through the mTOR pathway, specifically involving S6K1-mediated phosphorylation of GLI1 at Ser84." (PMID 39568072, 2024). "A potential alternative pathway, which might be involved in the Wnt-signaling pathway activation along the progression of Barrett’s esophagus, is the NF-κB-pathway, triggered by an increased TNF-α-receptivity in the more advanced stages of Barrett’s esophagus." (PMID 30841855, 2019). "Acid-dependent and inflammation-induced damage leads to progression of Barrett’s esophagus, which could potentially contribute to TNF-α-promoted tumor growth and metastasis via PI3K/Akt, GSK3β, and NF-κB." (PMID 30841855, 2019). "Inflammation is involved in the progression of Barrett’s esophagus and especially in EAC by an increased TNFα and TNFR1 signature." (PMID 34199909, 2021).
benign prostatic hyperplasia (16 papers, 2010 to 2025). A non-cancerous nodular enlargement of the prostate gland. "Thus, the pathogenic role of HIF-1α in prostatic hyperplasia gains extra support by the observed elevation of TNF-α and IL-1β by testosterone." (PMID 30154949, 2018). "The decreased IL-6 and TNF-α levels in ascites samples after treatment with EH alone and the association of Cph + EH were in accordance with the results of another previously cited in vivo study concerning castrated Sprague Dawley rats with benign prostatic hyperplasia." (PMID 38256751, 2024). "Systemic treatment with TNF antagonists reduces epithelial proliferation and macrophage accumulation in the prostate tissues from two mouse models of prostatic hyperplasia as well as human patients." (PMID 36072128, 2022). "Expression of genes encoding IDO, IL-6, IFN-γ, TNF-α, and their receptors was investigated in tumor tissues of PCa patients undergoing radical prostatectomy, in comparison with benign prostatic hyperplasia (BPH) specimens." (PMID 29896191, 2018). "To determine whether the cross-talk between benign prostatic hyperplasia prostate epithelium cells and infiltrating mast cells plays any role in activating the mast cells, we detected the TNF-α concentration in the conditioned medium." (PMID 28938626, 2017). "The complete mechanism of TNF-mediated promotion of prostatic hyperplasia is unknown." (PMID 36072128, 2022). "In a recent study it was shown that patients with benign prostatic hyperplasia (BPH) and AI who received TNFα antagonists prior to BPH diagnosis were less likely to develop BPH." (PMID 36371231, 2022).
calcinosis (16 papers, 2009 to 2025). Deposition of calcium in the tissues. "The TNF-α allele, called TNFα-308A, and the linkage disequilibrium of the HLA-B locus have been associated with a higher risk of calcinosis, prolonged disease course, and ulcerative skin disease." (PMID 24600322, 2014). "Given the association between calcinosis development and the TNF-α-308 A polymorphism, it appears that TNF-blocking drugs may be effective in treating calcinosis." (PMID 38166943, 2024). "Risk factors for the development of calcinosis include a delay in the diagnosis, delay in initiating treatment or inadequate treatment, tumor necrosis factor (TNF) alpha-308A genotype, presence of autoantibodies against nuclear matrix protein 2 (NXP2), and younger age at disease onset." (PMID 32550037, 2020). "Additionally, recent genotype investigations in JDM patients presenting with calcinosis have shown an association with a TNF-alpha-308A promoter polymorphism, which correlates with increased TNF-alpha production by peripheral blood mononuclear cells in the phenotype." (PMID 26579322, 2015). "Research on calcinosis lesions reveals the presence of TNF, interleukin-1 beta, and anti-inflammatory cytokines in the calcium milk extracted from these lesions." (PMID 38166943, 2024). "It was also noted that the reduction in number and size of calcinosis needed nearly 2 years on anti-TNF treatment." (PMID 32293539, 2020). "Cytokines such as IL-6, IL-1β, TNF-α, IL-1β, and IL-6 were also detected in serum, suggesting the role of activated macrophages in JDM-associated calcinosis." (PMID 32550037, 2020). "From those 11 patients, the calcinosis completely resolved in 4 of them in a median time of 2.8 [0.73–6.9] years and anti-TNF treatment was suspended in 3 of them with a median time of 4.6 years after the beginning of the drug." (PMID 32293539, 2020). "These patients all suffered from symptomatic calcinosis and were treated over a period of 8 to 30 months with additional Infliximab, a monoclonal antibody against TNF-α." (PMID 26579322, 2015). "Calcinosis (dystrophic calcification) is a frequent and distressing feature of JDM occurring in association with increased local production of TNFα." (PMID 24397895, 2014). "Raised levels of TNF-α have been demonstrated both in serum of patients with chronic DM and inside the calcium deposits (calcinosis cutis)." (PMID 24600322, 2014). "Recently, the effectiveness of the monoclonal antibody to TNF-alpha, infliximab, in the treatment of refractory juvenile dermatomyositis with calcinosis has been reported." (PMID 20181085, 2010). "Although we had a patient that showed evident reduction on calcinosis lesions only after 3 months on anti-TNF treatment, the majority needed a much longer time and in one case it was necessary to continue 10 years of anti-TNF treatment until the calcinosis completely resolved." (PMID 32293539, 2020). "Considering the high levels of TNF-alpha in patients with calcinosis, anti-TNF therapy may play a role in treating calcinosis." (PMID 32550037, 2020). "In our study, there was a reduction in the number and/or size of calcinotic lesions in 54% of the patients that were on infliximab/adalimumab and calcinosis completely resolved in 29% of them, although we cannot attribute these effects to anti-TNF treatment alone." (PMID 32293539, 2020). "Moreover, calcinosis has been more frequently associated with TNF-alpha-308A promoter polymorphism, which is associated with increased TNF- alpha production by peripheral blood mononuclear cells." (PMID 20181085, 2010). "Calcinosis is associated with prolonged disease activity in patients with JDM, a chronic course of illness, TNFα-308A allele (a pro-inflammatory promoter polymorphism) and increased production of TNFα, and with IL-1 cytokine polymorphisms." (PMID 19857267, 2009).
calcinosis (continued). "Genetic predisposition may also contribute; the TNF-α 308A allele, which is frequently found in JDM patients, is associated with overexpression of TNF-α, a pro-inflammatory cytokine linked to an increased risk of calcinosis." (PMID 40951214, 2025). "Anti-TNF-α therapy may be considered in treating JDM and DM-associated calcinosis." (PMID 37243003, 2023). "Therefore, the high expression of TNF-α could be part of the mechanisms involved in the calcinosis process and the severe tissular damage observed in the skeletal muscle during Querétaro infection." (PMID 24991553, 2014). "High levels of tumor necrosis factor (TNF) have been reported in patients with JDM who have experienced prolonged disease activity and calcinosis." (PMID 38166943, 2024). "The efficacy and safety of anti-TNF-α antibodies, such as infliximab and adalimumab, are reported in JDM for muscle and skin lesions, particularly for calcinosis." (PMID 39334579, 2024). "The expression of proinflammatory cytokines such as interleukin-1 (IL-1) and anti-tumor necrosis factor (TNF)-α, possibly induced by type I interferon (IFN I), has been described at the calcinosis site, suggesting macrophage activation." (PMID 37243003, 2023). "TNF has been identified in high levels in JDM patients who have a long disease course and calcinosis, which can be a debilitating complication." (PMID 32293539, 2020). "This highlights that an immediate improvement on the calcinosis should not be expected, and the anti-TNF treatment should not be stopped if an immediate improvement is not seen." (PMID 32293539, 2020). "Reports have been published concerning the treatment of calcinosis with colchicine, probenecid, aluminium hydroxide, diltiazem, high-dose immunoglobulin therapy, bisphosphonate preparations, and anti-TNFα preparations, but there is still no established regimen for this condition." (PMID 26640735, 2015).
cataract (16 papers, 2012 to 2024). Partial or complete opacity of the crystalline lens of one or both eyes that decreases visual acuity and eventually results in blindness. "TNF inhibitor use was associated with a higher frequency of cataracts (52 % vs 21 %; P = 0.001) and antinuclear antibody positivity (49 % vs 29 %; P = 0.04), although overall complication rates were not higher in these patients." (PMID 26879972, 2016). "Patients with cataracts exhibit notable increases in the expression levels of interleukin-6 (IL-6), IL − 1β, and tumor necrosis factor-α (TNF-α) compared to healthy individuals." (PMID 38327497, 2024). "Inflammation is indeed a key factor in the development of cataracts, as evidenced by the increased levels of IL-1, IL-1β, IL-6, and TNF-alpha in the vitreous fluid of cataract patients." (PMID 39556543, 2024). "The level of IL-12p40, MIP-1d, IL-7, IL-6R, BLC, TNF-a, IL-5 were elevated in the SG samples compared to the samples of the cataract patients." (PMID 32117217, 2020). "Compared with the cataract group, the concentration of IL-8, MMP-2, MMP-3, MMP-9, TGFβ-1, TGFβ-3, and TNF-α was significantly increased in subjects with JIAUwG or JIAUwoG." (PMID 29675026, 2018). "In the cataract cases, mean (± SD) IL-6, IL-8, MCP-1, TNF-α, PDGF-AA, PDGF-AB/BB, and VEGF levels were 35.6±109.5, 6.0±9.2, 971.3±500.5, 0.9±0.4, 30.1±15.7, 1.2±3.1, and 75.3±35.0 pg/mL, respectively." (PMID 26771310, 2016). "So, we focused in the present study on evaluation of selected pro-inflammatory cytokines (IL-1β, IL-6, IL-8, IL-17A, and TNF-α), anti-inflammatory cytokines (IL-4, IL-10, and IL-13), and the IL-1 receptor antagonist (IL-1Ra) in the aqueous humor of FECD and/or cataract eyes." (PMID 38792359, 2024). "Patients who received a TNF inhibitor were more likely to be ANA positive and have cataracts." (PMID 26879972, 2016). "However, patients treated with TNF inhibitors were more likely to be ANA positive and to have cataracts, again suggesting that these patients either had, or were perceived to have, more severe disease." (PMID 26879972, 2016).
cholesteatoma (16 papers, 2007 to 2023). A pathologic process characterized by the proliferation of keratinizing squamous epithelium resulting in the accumulation of keratin and cells in the middle ear and/or mastoid. "Numerous studies have pointed to the role of pro-inflammatory cytokines, such as TNF-α and IL-1 in the pathogenesis of cholesteatoma and bone destruction associated with the disease." (PMID 37998605, 2023). "Cholesteatoma is caused by chronic inflammation of the middle ear, and human cholesteatoma tissue secretes proinflammatory cytokines, such as IL-1β, IL-6, TNF-α, and PGE24,21." (PMID 37537159, 2023). "They concluded that TNF-α is present in granulation tissue adjacent to the cholesteatoma and causes bone resorption." (PMID 17505610, 2007). "The TNF-α is localized in all layers of the cholesteatoma matrix and is considered to have a vital role in bone resorption." (PMID 37762439, 2023). "In detail the expression of the cytokines, e.g. IL-1α IL-1β and IL-6, TNF-α, GM-CSF and the chemokine IL-8, is elevated in cholesteatoma." (PMID 33627146, 2021). "With TNFα being a major target gene of NF-κB and also an important cytokine involved in cholesteatoma progression, we investigated a potential pro-inflammatory feed-forward-loop of NF-κB target gene expression in ME-CSCs mediated by TNFα." (PMID 31947538, 2020). "Anyhow, the resulting TNFα-driven pro-inflammatory feed-forward-loop of NF-κB activation in ME-CSCs is in line with the already described involvement of TNFα in cholesteatoma progression and other pathogenesis via inflammatory cues." (PMID 31947538, 2020). "NF-κB target genes particularly include pro-inflammatory cytokines like TNFα, IL-1α, IL-1ß, IL-6, and IL-8 and were shown to be upregulated in cholesteatoma tissue." (PMID 31947538, 2020). "Bone resorption and destruction was also shown to be positively correlated to inflammation, the presence of bacterial lipopolysaccharides (LPS), and expression of inflammatory mediators like TNFα, IL-1α, and IL-6 in cholesteatoma." (PMID 31947538, 2020). "Simulating a bacterial infection characteristic for cholesteatoma, we observed a highly significant increase in expression of TNF-α in ME-CSCs in response to treatment with the TLR4-ligand LPS in comparison to ACSCs and untreated ME-CSCs." (PMID 29670222, 2018). "In human acquired cholesteatoma, the expression of proinflammatory cytokines (IL-1β, TNF-α and IL-6) and matrix metalloproteinases (MMP-2, MMP-8 and MMP-9) were up-regulated, and their expression levels were positively correlated with TREM-2 expression." (PMID 27934908, 2016). "We also confirmed significant upregulation of the downstream effector molecules TNF and IL1β in samples of cholesteatoma compared to samples of the EAS." (PMID 25922834, 2015). "The mRNA expression of TNFα and IL1β was significantly higher in cholesteatoma samples compared to the noninvasive squamous epidermal cells of external auditory skin (EAS)." (PMID 25922834, 2015). "The expression of the downstream and effector signaling genes TNFα and IL1β was therefore analyzed by QPCR in human samples of cholesteatoma of the middle ear." (PMID 25922834, 2015). "The tumor necrosis factor alpha (TNF-α) is present in cholesteatoma and it is related to bone erosion, as shown by different authors." (PMID 21860983, 2011). "Marenda and Aufdemorte19 (1995) attempted to find TNF-α and other cytokines in surgically collected cholesteatomas, comparing them with normal skin fragments from the external auditory meatus (EAM)." (PMID 17505610, 2007). "All studies agree on the importance of TNF-a in the bone resorption process present in cholesteatomas, and on the degree of destruction observed; however, there is no consensus as to its location." (PMID 17505610, 2007). "The plasmatic concentration of TNF-α in cholesteatoma patients with variable degrees of bone destruction is proportionally higher compared to normal patients." (PMID 17505610, 2007).
cholesteatoma (continued). "TNF-a, present in cholesteatomas, promotes bone resorption, along with other cytokines (RANKL and IL-1) related to complications." (PMID 17505610, 2007). "Cholesteatomas with increased bone destruction had a higher local amount of TNF-α,7,20,23 a finding seen both in acquired and congenital cholesteatomas." (PMID 17505610, 2007). "Bone resorption of cholesteatoma is affected by the Ki-67 weighted proliferation index, epidermal growth factor, matrix metalloproteinase-9, bone morphogenic protein, and cytokines such as TNF-alpha." (PMID 36766559, 2023). "Moreover, it was demonstrated that the expression of extracellular HMGB1 and DNA fragments in cholesteatoma keratinocytes induce the production of TNF-α and IL-1β, which leads to bone resorption and destruction associated with cholesteatoma." (PMID 37998605, 2023). "In previous studies, the level of TNFα has been correlated with bone erosion in cholesteatoma." (PMID 36013064, 2022). "In the presented study, we utilized our established human in vitro cholesteatoma stem cell model for treatments with lipopolysaccharides (LPS), tumor necrosis factor α (TNFα), and the TLR4-antagonist LPS from R. sphaeroides (LPS-RS) followed by qPCR, western blot, and immunocytochemistry." (PMID 31947538, 2020). "Moreover, the pro-inflammatory cytokines tumor necrosis factor (TNF)-α and IL-1β were up-regulated in acquired cholesteatoma." (PMID 26639190, 2015). "Our goal was to evaluate the role of TNF-a in Bone Resorption and its effect on cholesteatoma." (PMID 17505610, 2007). "TNF-α is increased both systemically and locally in aggressive cholesteatomas." (PMID 17505610, 2007). "All of the authors we reviewed agree that TNF-α is present in cholesteatomas." (PMID 17505610, 2007). "According to these authors, a TNF-α antagonist could be an important measure in the treatment of secretory otitis media, avoiding complications and cholesteatomas." (PMID 17505610, 2007). "TNF-α is found in cholesteatomas, promoting bone resorption by different routes." (PMID 17505610, 2007). "TNF-α is released in all middle ear infections, not only in cholesteatoma." (PMID 17505610, 2007). "It was then demonstrated that cholesteatomas can lead to bone resorption by releasing TNF-α." (PMID 17505610, 2007). "The growth and proliferation of cholesteatoma are closely linked to the upregulation of growth factors, such as epidermal growth factor (EGF) and keratinocyte growth factor (KGF) and its receptors, and cytokines, including IL-1, IL-6, and tumor necrosis factor α (TNF-α)." (PMID 37569652, 2023). "Thus, we hypothesize that a shift from the destructive M1 pathway toward the homeostatic M2 pathway through TNFα inhibition may represent a biological approach to the management of cholesteatoma." (PMID 36013064, 2022). "Therefore, it could be inferred that TREM-2 might amplify the inflammatory response in human acquired cholesteatoma and then increase the proinflammatory cytokines levels (IL-1β, TNF-α, and IL-6) while promoting MMP secretion." (PMID 27934908, 2016). "It is due to lytic enzymes such as collagenase and inflammatory mediators such as TNF alpha, IL-1,1L-6, IL-7, IFN beta, epidermal growth factor TGF-alpha, and matrix metalloproteinase, released by cholesteatoma matrix and granulation tissue." (PMID 37664290, 2023). "Candidate-gene approaches (analysing molecules known to regulate pathways altered in cholesteatoma) have found increased expression of interleukin-1 (IL1), tumor necrosis factor-alpha (TNFα), and defects in the regulation of epidermal growth factor receptor (EGFR)." (PMID 36920900, 2023). "Upon LPS challenge, we could detect a significantly higher expression of IL-1α, IL-1β, IL-6 and IL-8 in stem cells and of TNF-a, GM-CSF and CXCL-5 in stem cells and fibroblasts derived from cholesteatoma." (PMID 33627146, 2021).